BRAF (B-Raf proto-oncogene, serine/threonine kinase)
Diseases named in the same sentence as BRAF in open-access papers (continued):
Sharing a sentence is not in itself a finding about the gene and the disease.
serous carcinoma (38 papers, 2008 to 2025). "According to recent reports, ovarian serous borderline tumor (SBT) harboring the BRAF V600E mutation is associated with a lower risk of progression to low-grade serous carcinoma." (PMID 39001384, 2024). "After adjusting for age and stage, compared to wildtype SBTs, the risk of subsequent serous carcinoma remains significantly lower among women with BRAF-mutated SBTs [HR 0.27 (0.08 – 0.93), p = 0.038]." (PMID 31839880, 2019). "The estimated cumulative risk of developing serous carcinoma is lowest in the BRAF-mutated group, with the 10-year risk being 0.5% compared to 4.4% for wildtype and 2.3% for KRAS-mutated SBTs." (PMID 31839880, 2019). "KRAS and BRAF mutations are found in a proportion of low-grade serous carcinomas and, frequently, they are mutually exclusive." (PMID 29132324, 2017). "Mutations in either BRAF or KRAS can frequently be seen in low grade serous adenocarcinoma and borderline tumours of the ovary and seem to be mutually exclusive." (PMID 26197800, 2015). "Presence of KRAS and BRAF mutations was significantly more common in serous borderline ovarian tumors as compared to serous carcinomas (p = 0.0221; KRAS mutations) and (p < 0.0001; BRAF mutations); data not shown)." (PMID 19638206, 2009). "Our present results showing low frequencies of either KRAS or BRAF mutations in conventional high-grade serous carcinoma are consistent with our earlier reports." (PMID 19018267, 2008). "Similarly, BRAF mutations at codon 599 occur in 28% of SBTs and 30% of low grade serous carcinomas." (PMID 24868556, 2014). "There has been sufficient evidence to support that low-grade serous carcinoma (LGSOC) is distinct from high-grade serous (HGSOC) and is associated with BRAF and KRAS mutations." (PMID 39941911, 2025). "Previous studies have suggested BRAF V600E as an exclusive mutation in serous LMP and serous carcinomas." (PMID 37600581, 2023). "The mutation of KRAS/BRAF was observed in Western countries, whereas PIK3CA mutation was the main driver for Japanese low-grade serous carcinoma progression." (PMID 35621684, 2022). "For instance, two-thirds of low-grade serous carcinomas carry mutations in KRAS, BRAF or ERBB2 (refs 17, 18, 19)." (PMID 23839242, 2013). "At the molecular genetic level, low-grade serous carcinomas are characterized by frequent somatic sequence mutations in genes that are involved in signal transduction including KRAS, BRAF, ERBB2, and PIK3CA." (PMID 22028712, 2012).
serous carcinoma (continued). "BRAF and KRAS mutations are common in serous borderline tumors and low-grade serous carcinomas, but very rare in most serous carcinomas of high-grade." (PMID 19025622, 2008). "Low grade serous carcinomas are driven by BRAF and KRAS and represent <5% of ovarian tumors." (PMID 38352443, 2024). "After adjusting for age and stage, the risk of subsequent serous carcinoma was lower for SBTs harboring BRAF (HR 0.27, 95% CI 0.08–0.93), but not KRAS (HR 1.00, 95% CI 0.45–2.23) mutations, in comparison to wildtype SBTs." (PMID 31839880, 2019). "Among the low-grade serous carcinomas, there is a high frequency of activating mutations in the KRAS or BRAF genes; however, it remains unclear as to how these mutations contribute to tumor progression." (PMID 27128903, 2016). "Molecularly, low-grade serous carcinomas generally have low levels of chromosomal instability and carry frequent mutations in KRAS, BRAF, and ERBB2, while high-grade serous carcinomas tend to have high levels of chromosomal instability and frequently show mutations in TP5310." (PMID 25314936, 2015). "Unlike low grade serous carcinomas, BRAF mutations are not a feature of ovarian mucinous neoplasms of intestinal type." (PMID 24868556, 2014). "Together, KRAS or BRAF mutations are present in 68% of low-grade serous carcinomas, whereas they have not been identified in high-grade serous carcinoma." (PMID 23554638, 2010). "The significantly higher frequency of KRAS/BRAF mutations in non-serous type carcinomas compared with conventional high-grade serous carcinomas in this study is a finding of great interest." (PMID 19018267, 2008). "Similar but different BRAF and KRAS mutation roles in oncogenesis generate potential implications for the treatment of invasive mucinous ovarian carcinoma and highlight a challenge in its response to conventional chemotherapy compared to high-grade serous carcinomas." (PMID 38391958, 2024). "The BRAF mutation is most frequent in borderline tumors but not in invasive serous carcinomas." (PMID 37600581, 2023). "Furthermore, the frequency of KRAS and BRAF mutations in Japanese individuals with low-grade serous carcinomas is not known." (PMID 27128903, 2016). "Interestingly, in a previous study, KRAS (but not BRAF) mutation in ovarian serous borderline tumor is associated with recurrent low-grade serous carcinoma." (PMID 27128903, 2016). "However, mutations of BRAF oncogene are rare in invasive high-grade serous carcinoma and in non-serous ovarian tumors." (PMID 23554638, 2010). "Furthermore, epigenetic changes may be an important event in the carcinogenesis of some low grade serous carcinoma without KRAS or BRAF mutation." (PMID 27128903, 2016).
craniopharyngioma (37 papers, 2015 to 2025). A benign, partly cystic, epithelial tumor of the sellar region, presumably derived from Rathke pouch epithelium. "The use of targeted therapies is an evolving space for BRAF V600E mutated papillary craniopharyngiomas." (PMID 39664200, 2024). "One case report showed that a 39-year old with a BRAF V600E mutated craniopharyngioma first received neoadjuvant dabrafenib and trametinib, then received definitive radiosurgery." (PMID 39664200, 2024). "Histopathological analysis showed a papillary craniopharyngioma harboring classical BRAF V600E mutation." (PMID 35757402, 2022). "Histopathological analysis demonstrated a papillary Craniopharyngioma harboring the BRAF V600E mutation." (PMID 35757402, 2022). "Correlation of TrkA, β-catenin, cell cycle markers immunohistochemical score, and BRAF V600E mutation in craniopharyngioma." (PMID 35707464, 2022). "The relationship between immunohistochemical scores, BRAF V600E mutation, and clinical features of craniopharyngioma." (PMID 35707464, 2022). "We collected 61 craniopharyngioma (CP) specimens to investigate the expression of TrkA, β-catenin, BRAF gene mutation, and NTRK1 fusion in CP." (PMID 35707464, 2022). "In literature, there have been several reports of remarkable responses to BRAF and/or MEK inhibitors (vemurafenib, dabrafenib, and combination therapy) in craniopharyngiomas in various stages, since the discovery that PCPs often harbor BRAF gene mutation." (PMID 35155453, 2021). "Four out of six patients had mutations in BRAF, specifically the V600E missense mutation known to be expressed in the papillary subtype of craniopharyngioma." (PMID 31712784, 2019). "The expression pattern was nuclear and occasionally cytoplasmic in craniopharyngiomas that harbour known genetic mutations in CTNNB1 or BRAF and was located to well-characterised tumour compartments known to express progenitor markers." (PMID 30139767, 2019). "Previous craniopharyngioma sequencing studies have only focused on either codon hotspot mutations in BRAF and CTNNB1 or evaluations that were limited to 23- or 46-gene panels." (PMID 31712784, 2019). "As different types of mutations in the hedgehog, the Wnt, and BRAF/MAPkinase pathways define distinct subtypes of craniopharyngiomas, there seems to be signaling analogy in the pathways driving dentition and Rathke’s pouch formation." (PMID 29388014, 2018). "Virtually all craniopharyngiomas in childhood are of the adamantinomatous type (ACP), contrasting with adults in whom up to 10 % of craniopharyngiomas are papillary, and are now known to be driven by BRAF V600E mutations." (PMID 25990246, 2015). "For instance, BRAF/MEK inhibitors have shown significant efficacy in treating papillary craniopharyngiomas harboring BRAF-V600E mutations, while VEGF inhibitors like bevacizumab have demonstrated benefits in managing schwannomas and other highly vascularized tumors." (PMID 40113789, 2025). "A 49-year-old man with recurrent craniopharyngioma, harboring BRAF V600E mutation, has been treated with targeted therapy based on a combination of a BRAF-inhibitor, dabrafenib (150 mg, orally two times daily), and a MEK-inhibitor, trametinib (2 mg, orally two times daily)." (PMID 35155453, 2021). "However, the present results suggest that HK-II acts to drive glucose metabolism in PCP, or BRAF mutated craniopharyngiomas." (PMID 33420213, 2021). "Papillary craniopharyngiomas are characterized by the BRAF V600E mutation." (PMID 33420213, 2021). "BRAF V600E mutation and wild-type in craniopharyngiomas are discriminated with an AUC curve of 0.92 and ACC of 0.94 using two radiomics features while CTNNB1 mutation and wild-type in craniopharyngiomas are distinguished with an AUC curve of 0.95 and ACC of 0.91 based on three radiomics features." (PMID 30616515, 2019).
craniopharyngioma (continued). "As for other CNS tumours, further advances in deep-learning radiomics analysis of craniopharyngiomas could help in the future in avoiding biopsies, predicting the presence of BRAF mutation before surgery and thus favouring the use of targeted therapies as a neoadjuvant regimen." (PMID 39456573, 2024). "Similar results were demonstrated regarding the Vemurafenib + Cobimetinib (BRAF therapy + MEK inhibitor) combined treatment of BRAF-induced craniopharyngioma, which found that of 16 participants, 15 had a medium tumor reduction of 83%." (PMID 40943615, 2025). "This unique molecular signature led to the reclassification of adamantinomatous (CTNNB1) and papillary (BRAF) craniopharyngiomas as different pathologic entities by the Word Health Organization (WHO) in 2021." (PMID 39976897, 2025). "This case report seeks to add to the literature that shows clinical improvement of craniopharyngiomas with BRAF/MEK inhibition." (PMID 39664200, 2024). "In craniopharyngiomas (CPs), specifically the papillary subtype (PCP), BRAF gene mutations are often detected, potentially leading to cognitive impairments and attention deficits." (PMID 38315329, 2024). "This is a case showing improvement of a craniopharyngioma after treatment with BRAF and MEK inhibitor combinations." (PMID 39664200, 2024). "Current research on intelligent diagnosis methods focuses on predicting preoperative craniopharyngioma invasiveness, CTNNB1 and BRAF mutations, and postoperative prognosis." (PMID 39061172, 2024). "Together, these results support previous proteogenomic findings that aggressive MBs and ependymomas have lower immune infiltration compared with BRAF-driven LGGs and craniopharyngiomas." (PMID 37492101, 2023). "In craniopharyngiomas, the MAPK/ERK pathway can be activated via mutations in the BRAF gene (as in the PCPs subtype), or by paracrine stimulation by secondary mediators such as interleukins and growth factors (as in the ACPs variant)." (PMID 35323338, 2022). "BRAF and CTNNB1 mutations are found to be strongly correlated with the pathological subtypes of craniopharyngiomas, which means the diagnosis of pathological subtypes and gene mutations has great significance for the effective adjuvant targeted therapy." (PMID 35069406, 2021). "The present study showed common and strong expression (2+, 3+) of HK-II in 73% of PCP cases, and in 80% of BRAF V600E-positive craniopharyngioma cases (all PCP)." (PMID 33420213, 2021). "In this study, we intended to propose an effective noninvasive radiomics models for the estimation of BRAF and CTNNB1 mutations in craniopharyngiomas." (PMID 30616515, 2019). "Frequent somatic mutations of BRAF and CTNNB1 were identified in both histological subtypes of craniopharyngioma (adamantinomatous and papillary) which shed light on target therapy to cure this oncogenic disease." (PMID 30616515, 2019). "The aim of this study was to investigate the noninvasive MRI-based radiomics diagnosis to detect BRAF and CTNNB1 mutations in craniopharyngioma patients." (PMID 30616515, 2019). "Such a model would be of help in refining the role of BRAF inhibitors and in solving the controversy of the cell‐of‐origin of the craniopharyngioma subtypes." (PMID 28414891, 2017). "In CNS, BRAF alterations are found in variable frequencies across a wide spectrum of diverse neoplasms, such as various glial and glioneuronal tumours, craniopharyngiomas, LCH and brain metastases." (PMID 27760550, 2016). "VE1 staining discriminates papillary carcinomas from adamantinomatous craniopharyngiomas expressing β-catenin but not having BRAF mutations." (PMID 39939491, 2025). "First-line treatment of newly diagnosed craniopharyngiomas after resection is BRAF/MEK inhibition." (PMID 39664200, 2024). "Recently, a method was reported for diagnosing molecular variants (BRAF mutated or nonmutated craniopharyngioma) by preoperative MR imaging and CT31,32." (PMID 33420213, 2021).
craniopharyngioma (continued). "Preoperative FDG-PET could be important in considering neoadjuvant BRAF inhibitor treatment strategy for craniopharyngioma in the future." (PMID 33420213, 2021). "Recent evaluations have also shown that craniopharyngiomas have a low frequency of somatic mutations other than BRAF V600E mutation and are not genomically complex." (PMID 35155453, 2021). "In addition, GLUT-1 expression was found in 90% of BRAF V600E-positive craniopharyngioma cases (all PCP)." (PMID 33420213, 2021). "However, while empiric treatment is enticing to avoid surgical intervention entirely, it is cautioned, as approximately 5% of histopathologic- and radiographic-appearing craniopharyngioma do not harbor the BRAF V600E mutation." (PMID 39976897, 2025). "However, expressions of TRKA, cyclin D1, and P16 and their relationship with BRAF V600E mutation in craniopharyngioma have not been reported." (PMID 35707464, 2022). "Recent advances in molecular biology have introduced targeted therapies, such as BRAF and MEK inhibitors, which show potential benefits in craniopharyngioma patients, particularly in the PCP." (PMID 40433410, 2025). "Only 1 patient with craniopharyngioma had immunohistochemistry staining revealing beta-catenin positive and BRAF V600E negative." (PMID 40351830, 2025). "In necessary conditions, immunohistopathology for BRAF V600E can be made to confirm the pathological diagnosis, since the majority of craniopharyngiomas stain with the BRAF V600E antibodies, but not specifically the developmental cysts." (PMID 39939491, 2025). "Rapid direct immunohistochemical methods are feasible but no study has tested the BRAF V600E antibody in the setting of craniopharyngioma intraoperative diagnosis." (PMID 35757402, 2022).
gastrointestinal stromal tumor (36 papers, 2012 to 2025). "Gastrointestinal stromal tumors: BRAF V600E mutations are also found in 0.6 to 3.9% of gastrointestinal stromal tumors (GISTs), acting as tumor-agnostic markers predictive of response to BRAF inhibitors, similar to NTRK fusions." (PMID 40332392, 2025). "Approximately 8% of the gastrointestinal stromal tumors devoid of KIT/ PDGFRA mutations bear the BRAF mutation." (PMID 37454137, 2023). "The BRAF mutation has also been reported in a small subset of Gastrointestinal Stromal Tumors (GIST)." (PMID 27097112, 2016). "An association between the PDGFRα and BRAF(V600E) mutation is also observed in wild type PDGFRα gastrointestinal stromal tumors (GISTs) which acquire the BRAF(V600E) mutation when they develop resistance to PDGFRα-I imatinib." (PMID 24732172, 2014). "Our purpose is to define the distribution of c-KIT, PDGFR and BRAF mutations in a population-based cohort of gastrointestinal stromal tumors (GIST) patients and correlate them with anatomical site, risk classification and survival." (PMID 25885906, 2015). "Activating oncogenic mutations of BRAF have been described in patients with gastrointestinal stromal tumor (GIST), but treatment of GIST with BRAF inhibitors and mechanisms of mediating the emergence of resistance in GIST have not been reported." (PMID 23470635, 2013). "Case 2 (patient ID 501) is a 68-year-old man with metastatic gastrointestinal stromal tumor with BRAF V600E and CDKN2A alterations, who presented after the tumor progressed on BRAF/MEK-targeted therapy." (PMID 33427211, 2021). "About 10–15% of adult, and most pediatric, gastrointestinal stromal tumors (GIST) lack mutations in KIT, PDGFRA, SDHx, or RAS pathway components (KRAS, BRAF, NF1)." (PMID 27974047, 2016). "Furthermore, the drug repurposing approach is even more applicable for STS with oncogenic mutations: gastrointestinal stromal tumors (GIST) with activating mutations in c-KIT, PDGFA and BRAF, myxoid round cell liposarcoma with activating mutation in PI3K/Akt signaling component PI3CA." (PMID 32317857, 2020). "Gastrointestinal stromal tumors with BRAF V600E do not respond to treatment with imatinib and sunitinib, but a successful case of treatment with regorafenib has been described." (PMID 36900287, 2023).